CXCL3 (C-X-C motif chemokine ligand 3)
Diseases named in the same sentence as CXCL3 in open-access papers (continued):
Sharing a sentence is not in itself a finding about the gene and the disease.
tumor (continued). "Specifically, the chemokine‐related genes, CXCL1, CXCL2, CXCL3, and IL‐1β, were up‐regulated, while CXCR1 was down‐regulated in tumor tissue during the progression of HCC." (PMID 27682863, 2016). "Expression levels of multiple genes encoding for cytokines or cytokine receptors over-expressed in tumor cells or ascites fluid, such as CXCL1, CXCL2, CXCL3, IL8, IL6, IL6R, and CXCR4 were reduced in OV3/COX1KD cells." (PMID 25972361, 2015). "It must be noted however, that expression of many of the chemokines were most often found to be downregulated in the NSCLC tumours as follows CXCL1 (64.9%, p<0.01), CXCL2 (81.1%, p<0.01), CXCL3 (59.5%)." (PMID 21298036, 2011). "In renal cell cancer the levels of CXCL1, CXCL3 and CXCL8 were elevated compared to controls and in receptor negative (CXCR2−/−) mice there was a corresponding reduction in tumour growth." (PMID 21298036, 2011). "Mechanistically, this subset responds to hypoxia by expressing VEGFA to directly promote tumor angiogenesis while highly expressing the chemokines CXCL2, CXCL3, and CXCL8 to establish a chronic inflammatory microenvironment that indirectly fosters tumor progression and vascularization." (PMID 41514936, 2026). "Knockdown of Ccl20 and Cxcl3 notably decreased tumor growth in nude mice, but there was no substantial difference between the short hairpin Cxcl3 (sh-Cxcl3) and sh-Ccl20 groups." (PMID 40179015, 2025). "Among them, the chemokine family, including CC (e.g., CCL1, CCL3, CCL5, CCL7, and CCL15), CXC (e.g., CXCL1, CXCL3, CXCL5, and CXCL10), XC (e.g., XCL1 and XCL2), and CX3C (e.g., CX3CL1), plays a pivotal role in tumor development, metastasis, and chemotherapy resistance 30-33." (PMID 40740234, 2025). "Notably, members of the CXC chemokine family, including CXCL1, CXCL2, CXCL3, CXCL5 and CXCL8, function through the activation of CXCR1 and CXCR2, playing a key role in promoting tumour angiogenesis." (PMID 39161078, 2025). "In addition, we found that CAF_C3 highly expressed CXCL3 and CXCL8, which are known to play critical roles in tumor progression." (PMID 40725006, 2025). "CXCR2 ligands such as CXCL1, CXCL2, CXCL3, and CXCL5 are highly expressed in the tumor microenvironment of KRAS-mutant preclinical models, although their elevated secretion is often attributed to stromal or immune cells rather than direct production by KRAS-mutant tumor cells." (PMID 40524071, 2025). "Interestingly, the scRNA‐seq data revealed the upregulation of CXCL2, CXCL3, CXCL8, and CCL4 in metastatic tumor cells compared to primary tumor cells or normal cells." (PMID 39985269, 2025). "Subclusters 4 and 5 may be related to tumor invasion and metastasis (migration factors CXCL3 and CXCL1; adhesion factors CEACAM6 and EMP1), suggesting that they may be tumor cell clusters with a greater degree of malignancy." (PMID 38927691, 2024). "Tumor cells that were treated with EZH2 inhibitor alone or in combination with anti-PD1 had increased H2-K1, B2m, and Ifngr1 expression, and decreased expression of neutrophil-recruiting chemokines such as Cxcl3, Cxcl5, and Ppbp (a.k.a Cxcl7)." (PMID 38265267, 2024). "However, tumor cells possess intricate mechanisms, including the recruitment of alternative MDSC-inducing chemokines such as CXCL3/CXCR." (PMID 39456702, 2024). "In addition, neutrophils can also secrete bioactive substances that promote tumor progression, including VEGF, MMP9, Oncostatin M (OSM), IL-1β, ​​TNF-a, IL-8, CXCL3, ROS." (PMID 37644468, 2023).
tumor (continued). "We also observed that MDSC-secreted VEGFA and multiple chemokines CCL2, CXCL1, CXCL2, CXCL3, and CXCL8 could act on endothelial cells via VEGFA-KDR/FLT1 and CCL2/CXCLs-ACKR1 interactions, which were crucial for tumor angiogenesis." (PMID 37475874, 2023). "Comparing immune cells and immune-related gene expression across different FAT statuses, we found that in FAT mutant STAD, chemokines, such as CCL3, CCL4, CXCL1, CXCL3, CXCL9, and CXCL10, recruited and activated cytotoxic T lymphocytes in the tumor tissue to perform an antitumor effect." (PMID 35836939, 2022). "CXCL3 levels correlated with carcinoembryonic antigen (CEA) levels, a clinical tumor marker of CRC." (PMID 35664357, 2022). "In addition, NDRG3 also up-regulate the expression of angiogenic chemokine 43 (CXCL1, CXCL3 and CXCL5), enhance the expression of Angiogen-44, thereby ultimately promoting tumor progression." (PMID 36619553, 2022). "An in-depth understanding of the tumor microenvironment and tumorigenesis mechanism would clarify whether CXCL4, along with CXCL3 and 8, exerts potential synergistic effects on HNSC tumorigenesis." (PMID 34247149, 2021). "ELR chemokines include CXCL8, CXCL3, and CXCL1, which promote tumor angiogenesis." (PMID 32462020, 2020). "Based on these results, it is plausible that IL-33 secreted from stellate cells or CAFs acts on other cells, such as macrophages, that are reported to express ST2L and CXCL3, rather than on tumor cells themselves to stimulate the secretion of CXCL3." (PMID 32340025, 2020). "A more recent study shows that the chemotherapeutic drug cyclophosphamide induces the expression of CXCL3 by tumor cells, leading to intratumoral migration of CD4+ T cells expressing cytotoxic molecules, which are able to eradicate the tumor through specific tumor immunity." (PMID 29037250, 2017). "Real-time PCR results indicated that tumor tissue samples expressed a higher level of CXCL3 compared with the corresponding adjacent non-cancerous tissue samples." (PMID 27255419, 2016). "We analyzed CXCL3 mRNA expression in 30 HCC patients’ tissue and para-tumor tissue samples." (PMID 27255419, 2016). "Nanostring data from BRD4 inhibitor–treated tumors also revealed decreased tumor expression of chemokines important for MDSC recruitment to tumors including CXCL5, CXCL3, and CCL2, suggesting that the reduced intratumoral MDSC levels could be caused by impaired MDSC migration into the TME." (PMID 40762981, 2025). "Interestingly, knockdown of Cxcl3, but not of Ccl20, notably increased the frequency and activity of tumor-infiltrating granzyme B+ (GzmB+) CD8+ T cells." (PMID 40179015, 2025). "Moreover, RNA-seq results showed that NAT10 promoted the transcription of multiple critical cytokines such as CXCL3 and CXCL8 and suppressed CXCL10, CXCL11 and so on, which are important for the recruitment of immune cells, angiogenesis, tumor microenvironment remodeling, and cancer progression." (PMID 37914704, 2023). "In addition, we also in vitro and in vivo explored the potential clinical significance and action mechanism of CXCL3 in HNCSS tissues and tumor cells, which may provide a novel idea for the future development in prevention, diagnosis and treatment of HNCSS." (PMID 34870709, 2021). "Notably, the heterogeneity of the CXCL3 levels was observed in tumor samples (−, absent; +, weak; ++, moderate; and +++, strong)." (PMID 32614785, 2020). "Tumor upregulated chemokines included the followings: CXCL5 (138 fold increase); CCL25 (70 fold increase); CXCL11 (26 fold increase); CXCL6 (20 fold increase); CXCL1 and CXCL10 (11 fold increase); CXCL3 (8 fold increase); and CXCL9, CXCL2, and CCL3L1 (6 fold increase)." (PMID 29088818, 2017). "The overall survival analysis revealed that the high expression of CXCL3 in the serum was closely associated with poor outcomes in HCC patients, and patients with low CXCL3 expression levels were more likely to have a capsule around the tumor tissue and possess no vascular invasion." (PMID 27255419, 2016).
tumor (continued). "However, when the dose of CXCL3 increases to a certain value, it actually inhibits malignant behaviors of these tumor cells and induces down-regulated expression of ERK, suggesting the inhibitory effect exertd by high doses of CXCL3 may be related to its blockade on the ERK signal." (PMID 38031087, 2023). "Consistent with this, we found all angiogenesis-related genes to be significantly upregulated in non-pCR patients, with VEGFA, CXCL8, CXCL2, CXCL3, and HBEGF identified as core drivers of tumor angiogenesis and immune escape." (PMID 41514936, 2026). "shCXCL3 treatment inhibited the tumor-sphere formation ability of CD133+ PLC/PRF/5 cells, and the tumor-sphere formation ability of CD133− PLC/PRF/5 cells was also impaired after CXCL3 knockdown, though it was not so obvious compared with CD133+ cell group." (PMID 27255419, 2016). "The absence of CD14-positive cells within the tumour epithelium in ACP is unexpected as the β-catenin-accumulating epithelial whorls (cell clusters) express a variety of chemo-attractant cytokines (e.g., members of the CCL and CXCL family of chemokines including CCL2, CXCL1, CXCL3, CXCL11)." (PMID 39127699, 2024).
cancer (85 papers, 2007 to 2025). A tumor composed of atypical neoplastic, often pleomorphic cells that invade other tissues. "It is now widely accepted that CXCL3 is upregulated in various human tumors, and its high expression has been associated with adverse clinical and pathological characteristics in cancer patients." (PMID 41259383, 2025). "The cancer genome atlas (TCGA)-COAD data analysis revealed that CXCL3 mRNA is highly expressed and has high clinical diagnostic accuracy in COAD." (PMID 38031087, 2023). "CXCL3 is associated with the invasion and metastasis of various cancers and CXCL3 and CXCL6 are involved in the invasion and migration of various cancers." (PMID 35602512, 2022). "Understanding the changes in CXCL3 expression can cause severe dysfunction, and even lead to cancers such as HNSCC, requires further research." (PMID 34870709, 2021). "This was associated with a decrease in the levels of the anti‐inflammatory molecule adiponectin and the number of GLUT4‐positive cancer‐associated adipocytes, as well as an increase in IκBα phosphorylation levels, Cxcl3 expression, and the accumulation of infiltrating CD206+ protumor N2 TANs." (PMID 40751595, 2025). "In addition, CXCL1 expression was extremely correlated with CCL20, CXCL8 and CXCL3 cancer-associated chemokines expression." (PMID 35764974, 2022). "In agreement with our experimental data and the HMS LINCS analysis, we found that CXCL8 expression is strongly correlated with CXCL1 (R2 = 0.59), followed by CXCL2 (R2 = 0.49) and CXCL3 (R2 = 0.48), across all DepMap cancer cell lines." (PMID 40833805, 2025). "CXCR-2 ligands include CXCL-1, CXCL-2, CXCL-3, CXCL-5, IL-6, CXCL-7 and IL-8, and overall CXCLs/CXCR-2 pathway is implicated in cancer and inflammation." (PMID 38672477, 2024). "Remarkably, the expression of iMSC signature genes such as IL6 and CXCL3 decreased after a full elimination of the cancer cells." (PMID 37958322, 2023). "We found the expression of CXCL3 to be relatively high and stable in cancer tissue and the plasma of CRC patients." (PMID 35664357, 2022). "The CXC chemokines (e.g., CXCL1, CXCL2, CXCL3, CXCL5, and CXCL8) are significantly upregulated in most cancers and positively associated with cancer metastasis and chemo-resistance." (PMID 36612163, 2022). "Upregulation of CXCL1 and CXCL3 has been found to potentiate infiltration of immunosuppressive neutrophils, favoring cancer cells escaping from immune surveillance." (PMID 36612163, 2022). "Spearman's rank correlation analysis showed that the level of CXCL3 in plasma of CRC patients was positively related to the expression of CXCL3 in cancer tissue (r = 0.78, P < 0.01)." (PMID 35664357, 2022). "Lingonberry extract also promoted the apoptosis of HepG2 cancer cells, inhibiting their proliferation, migration, and invasion by regulating the expression of CXCL3." (PMID 35802745, 2022). "A total of 73 genes with pearson correlation coefficient (PCC) ≥ 0.30 were found, in which cancer-associated chemokines CCL20, CXCL8 and CXCL3 were extremely associated with CXCL1 expression." (PMID 35764974, 2022). "Pearson's correlation analysis assessed relationships among plasma CXCL3, cancer tissue CXCL3, and plasma carcinoembryonic antigen (CEA)." (PMID 35664357, 2022). "This study demonstrated the expression of CXCL3 in CRC cancer tissue to be significantly higher than in matched adjacent tissue (P < 0.001)." (PMID 35664357, 2022). "In summary, this study analyzed the expression of CXCL3 in cancer tissue and plasma of CRC patients and found relationships among CXCL3 and patient clinic pathological characteristics." (PMID 35664357, 2022). "Plasma CXCL3 was positively related to CXCL3 in cancer tissue (r = 0.78, P < 0.01), and also to plasma CEA (r = 0.50, P < 0.01)." (PMID 35664357, 2022). "CXCL10, CXCL8, CXCL2, and CXCL3 can also induce cell growth and proliferation and are putative autocrine or paracrine growth factors in cancer." (PMID 33939688, 2021).
cancer (continued). "The genes (CXCL1, CXCL3, CXCL8, NFKBIB, and SRC) associated with chemokine pathway signaling result in changes in the cellular microenvironment that favor cancer and transformation in L-LVL cells." (PMID 34680563, 2021). "CXCL3-primed CAFs promoted cancer metastasis and expression of CXCL3 was correlated with poor patient survival." (PMID 34203869, 2021). "Most of the genes in the subnetworks were inflammatory cytokines and participated in TNF signaling pathways and pathways in cancer, such as Ccl2, Ccl20, Csf1, Cx3cl1, Cxcl1, Cxcl3, Il6, Birc3, Map3k8, Nos2, Nfkb2, Tnfrsf1b, and Vcam1." (PMID 33042984, 2020). "The expression of CXCL1, CXCL3, CXCL2, CCL20, and IL6 are enriched in residual cancer and are associated with lesser response the chemotherapy when highly expressed at baseline." (PMID 30967156, 2019). "Inflammatory infiltrates were wider in both Calu-6 and SK-MES tumors from hrIL-27-treated mice than in control tumors, because of the significant (P < 0.05) increase in their granulocyte and macrophage content, along with cancer cell expression of CXCL3." (PMID 25638163, 2015). "The MB-downregulated genes include cancer-associated cytokines/chemokines (e.g. CXCL1, CXCL2, CXCL3, CXCL14, IL1A, IL1B, IL6, IL8) and matrix metalloproteinases (MMP1,MMP9)." (PMID 25642713, 2015). "Likewise, prostate epithelial cells prompt stromal cells to secrete proinflammatory and cancer-promoting chemokine (CXCL3)." (PMID 38745115, 2024). "Besides chemokines of NF-κB signaling, the inflammatory cytokines TNF-α and LIF were highlighted to play a role in interaction with CXCL-8 in cancer development and the chemokines CXCL3 and CXCR2 in their role in cell migration." (PMID 37048115, 2023). "Although many aspects of CXCL3 in several types of human cancers have been explored, its clinical significance and mechanism of action in HNSCC remain unclear." (PMID 34870709, 2021). "These evidences suggest that CXCL1, CXCL2, and CXCL3 may be indirectly involved in the genesis and progression of carcinoma through the mobilization of human immune cells." (PMID 34269159, 2021). "This was associated with decreases in Cxcl3 expression, vessel density and accumulation of cancer-associated neutrophils but not cancer-associated macrophages." (PMID 32340025, 2020). "Evidence suggests that CXCL3 promotes the invasiveness of cancerous cells and may be a potential target for cancer therapy." (PMID 32430842, 2020). "Interestingly, a recent report showed that Cxcl3 promotes the proliferation and tumorigenesis of hepatocarcinoma cancer stem cells." (PMID 28018222, 2016). "Upregulation of CXCL1 and CXCL3 has previously been observed in CRCs and other cancer types." (PMID 17201907, 2007). "This suggests that targeting CXCL3 could potentially enhance the efficacy of cancer treatments." (PMID 40517358, 2025). "TNF-α expression was observed to upregulate expression of several cancer-associated genes in the epithelial cells which include extracellular matrix (ECM) remodeling genes such as MMP9, PLAU, FN1 and ICAM1, chemokines such as CCL2, CXCL2, CXCL3 and CXCL10 and regulatory genes such as UBD and PTGS2." (PMID 34946170, 2021). "G-CSF also formed a network with other proteins involved in cancer growth and progression, such as POU2F2, HEF1, and CXCL3." (PMID 39739128, 2024). "TCGA database indicated that among several ligands, CXCL1, CXCL3, CXCL5, CXCL7 and CXCL8 (ligands for CXCR2) and CCL15 (ligand for CCR1) were particularly upregulated in CRC tissues compared with other cancers." (PMID 38750114, 2024). "Results indicated that chemokines CXCL3 and CXCL5 gene expression were higher in the A3 and A5 than in T2 cell lines, indicating that they were important for cancer initiation either by the effect of radiation or estrogen." (PMID 39201290, 2024).